GPER1 (G protein-coupled estrogen receptor 1)
Description:
G protein-coupled estrogen receptor that binds to 17-beta-estradiol (E2) with high affinity, leading to rapid and transient activation of numerous intracellular signaling pathways. Stimulates cAMP production, calcium mobilization and tyrosine kinase Src inducing the release of heparin-bound epidermal growth factor (HB-EGF) and subsequent transactivation of the epidermal growth factor receptor (EGFR), activating downstream signaling pathways such as PI3K/Akt and ERK/MAPK. Mediates pleiotropic functions among others in the cardiovascular, endocrine, reproductive, immune and central nervous systems. Has a role in cardioprotection by reducing cardiac hypertrophy and perivascular fibrosis in a RAMP3-dependent manner. Regulates arterial blood pressure by stimulating vasodilation and reducing vascular smooth muscle and microvascular endothelial cell proliferation. Plays a role in blood glucose homeostasis contributing to the insulin secretion response by pancreatic beta cells. Triggers mitochondrial apoptosis during pachytene spermatocyte differentiation. Stimulates uterine epithelial cell proliferation. Enhances uterine contractility in response to oxytocin. Contributes to thymic atrophy by inducing apoptosis. Attenuates TNF-mediated endothelial expression of leukocyte adhesion molecules. Promotes neuritogenesis in developing hippocampal neurons. Plays a role in acute neuroprotection against NMDA-induced excitotoxic neuronal death. Increases firing activity and intracellular calcium oscillations in luteinizing hormone-releasing hormone (LHRH) neurons. Inhibits early osteoblast proliferation at growth plate during skeletal development. Inhibits mature adipocyte differentiation and lipid accumulation. Involved in the recruitment of beta-arrestin 2 ARRB2 at the plasma membrane in epithelial cells. Also functions as a receptor for aldosterone mediating rapid regulation of vascular contractibility through the PI3K/ERK signaling pathway. Involved in cancer progression regulation. Stimulates cancer-associated fibroblast (CAF) proliferation by a rapid genomic response through the EGFR/ERK transduction pathway. Associated with EGFR, may act as a transcription factor activating growth regulatory genes (c-fos, cyclin D1). Promotes integrin alpha-5/beta-1 and fibronectin (FN) matrix assembly in breast cancer cells.
Synonyms: FEG-1; LYGPR; mER; CEPR; CMKRL2; DRY12; GPER; GPR30; GPCR-Br; LERGU; LERGU2
Tractability: Small molecule: a structure with a bound ligand is known; a high-quality ligand is known; it belongs to a druggable protein family. Antibody: its Gene Ontology location is reachable by antibodies, with high confidence; UniProt places it where antibodies can reach, with medium confidence; UniProt predicts a signal peptide or a membrane-spanning region. PROTAC: UniProt records ubiquitination sites on it; a small molecule that binds it is known.
Target class: Family A G protein-coupled receptor; Steroid-like ligand receptor; Membrane receptor; Small molecule receptor (family A GPCR); Lipid-like ligand receptor (family A GPCR)
Chemical probes: LNS-8801, ML050
Gene: Protein-coding gene on chromosome 7 (1,082,208 to 1,094,511, forward strand). Ensembl gene ENSG00000164850.
Subcellular location: Nucleus; Cytoplasm; Cytoplasm, perinuclear region; Cytoplasm, cytoskeleton; Cell membrane; Basolateral cell membrane; Cytoplasmic vesicle membrane; Early endosome; Recycling endosome; Golgi apparatus membrane; Golgi apparatus, trans-Golgi network; Endoplasmic reticulum membrane; Cell projection, dendrite; Cell projection, dendritic spine membrane; Cell projection, axon; Postsynaptic density; Mitochondrion membrane
Subcellular location (Human Protein Atlas): Nucleoli; Cytosol; Nucleoplasm; Vesicles
Pathways (Reactome):
Signal Transduction: G alpha (i) signalling events; GPER1 signaling; Peptide ligand-binding receptors
Gene Ontology:
Molecular function: chromatin binding; nuclear estrogen receptor activity; protein binding; steroid binding; steroid hormone binding; G protein-coupled estrogen receptor activity; G protein-coupled receptor activity
Biological process: adenylate cyclase-activating G protein-coupled receptor signaling pathway; cellular response to estradiol stimulus; cellular response to peptide hormone stimulus; cellular response to tumor necrosis factor; G protein-coupled receptor signaling pathway; negative regulation of cell cycle process; negative regulation of ERK1 and ERK2 cascade; negative regulation of gene expression; negative regulation of inflammatory response; negative regulation of leukocyte activation; negative regulation of phosphatidylinositol 3-kinase/protein kinase B signal transduction; negative regulation of vascular associated smooth muscle cell proliferation; nuclear receptor-mediated steroid hormone signaling pathway; positive regulation of cardiac vascular smooth muscle cell differentiation; positive regulation of cell migration; positive regulation of cell population proliferation; positive regulation of epidermal growth factor receptor signaling pathway; positive regulation of ERK1 and ERK2 cascade; positive regulation of G protein-coupled receptor signaling pathway; positive regulation of gene expression; positive regulation of inositol trisphosphate biosynthetic process; positive regulation of phosphatidylinositol 3-kinase/protein kinase B signal transduction; positive regulation of protein localization to plasma membrane; positive regulation of protein phosphorylation; positive regulation of release of sequestered calcium ion into cytosol; and 27 more
Cellular component: cytoplasmic vesicle membrane; cytosol; early endosome; endoplasmic reticulum; endoplasmic reticulum membrane; Golgi apparatus; keratin filament; nuclear envelope; nucleolus; nucleoplasm; nucleus; perinuclear region of cytoplasm; plasma membrane; recycling endosome; trans-Golgi network; axon; axon terminus; cytoplasm; dendrite; dendritic shaft; dendritic spine head; dendritic spine membrane; mitochondrial membrane; postsynaptic density; presynaptic active zone; and 5 more
Genetic constraint (gnomAD): Loss-of-function variants: 8 observed, 6.11 expected, observed/expected ratio (o/e) 1.31, 90% interval 0.75 to 1.9. That is too few expected variants to judge how well the gene tolerates losing a copy. Missense variants: 441 observed, 532.71 expected, observed/expected ratio (o/e) 0.83, 90% interval 0.76 to 0.9. Synonymous variants: 263 observed, 249.56 expected, observed/expected ratio (o/e) 1.05, 90% interval 0.95 to 1.17.
Homologues: Orthologues: macaque GPER1 (98% identical), guinea pig GPER1 (89% identical), dog GPER1 (88% identical), mouse Gper1 (87% identical), rat Gper1 (86% identical), rabbit GPER1 (83% identical), pig GPER1 (76% identical), tropical clawed frog gper1 (67% identical), zebrafish gper1 (63% identical). Paralogues in human: ACKR5 (26% identical).
Diseases named in the same sentence as GPER1 in open-access papers:
GPER1 is named in the same sentence as 328 diseases in open-access papers, as found by Europe PMC text mining. Sharing a sentence is not in itself a finding about the gene and the disease. The quoted sentences say what the papers report.
breast carcinoma (358 papers, 2007 to 2026). "Altered hormonal balance, increased breast cancer risk, especially hormone-dependent types; Epigenetic modifications influence GPER-1 expression.Tamoxifen-mediated GPER-1 activation sustains CSCM stemness and viability." (PMID 39936103, 2025). "GPER-1, a transmembrane protein, operates independently of ERα and ERβ and has been implicated in estrogen-mediated signaling pathways in breast cancer." (PMID 41200178, 2025). "The T allele of the GPER1 gene SNP rs11544331 triggers the expression of the P16L variant, which promotes the migration of breast cancer cells." (PMID 37921845, 2023). "In contrast, GPER1 expression has been associated with reduced response or resistance to tamoxifen therapy in patients with breast cancer, mediated by regulating HMGB1 (high mobility group box 1)." (PMID 36060947, 2022). "Tamoxifen at 1 μM continuously exposed breast cancer cells for 7 days upregulates GPER-1 and increases cell proliferation associated with kinin B1 receptor induced signaling." (PMID 36558071, 2022). "In patients with breast cancer, GPER1 downregulation in the tumor tissue is associated with poor survival." (PMID 36060947, 2022). "Recently, phytoestrogens such as isoflavones also activate G protein-coupled receptor GPR30 (also known as GPER-1) associated with several physiopathological disorders and especially in estrogen-dependent diseases such as breast cancer." (PMID 34209224, 2021). "Signaling through GPER-1 has been shown to trigger the expression of IL-1β and IL-1R1 in cancer-associated fibroblasts and breast cancer cells, respectively." (PMID 33117280, 2020). "GPER-1 mRNA has been detected in several breast cancer cell lines and its expression has been associated with the increased proliferation rate exhibited by these cells." (PMID 33117280, 2020). "Here, GPER1 and miRNAs involvement in breast cancer progression is reviewed, underlining the more recent action of GPER1 in modulating miRNA expression." (PMID 33374170, 2020). "Of note, an intranuclear localization of GPER1 it has also been shown in the more representative components of tumor stroma, especially of breast cancer, named cancer associated fibroblasts (CAFs)." (PMID 33374170, 2020). "It has also been reported that, in breast cancer cells, the estrogenic stimulation of GPER1 causes activation of the Gαs protein which, in turn, leads to adenylyl cyclase activation and cAMP accumulation." (PMID 33374170, 2020). "In agreement with the results obtained by us in the present study we have recently found that GPER-1 is associated with better patient survival in breast cancer patients and have been recently confirmed for inflammatory breast cancer." (PMID 23849542, 2013). "In addition, GPER-1 has also been observed to be associated with several pathological processes, especially breast cancer." (PMID 39936103, 2025). "Importantly, through its activation by environmental and synthetic estrogens, GPER-1 is associated with hormone therapy resistance in breast cancer." (PMID 39936103, 2025). "GPER1 is a Gs-coupled membrane-associated estrogen receptor that elicits an array of intracellular signaling pathways, including an elevation in [Ca2+]i, in breast cancer cells." (PMID 38203629, 2023). "Moreover, GPER1 has attracted considerable interest because of its potential association with a variety of cancer types, including breast cancer." (PMID 37947649, 2023). "On the other hand, in breast cancer, the presence of GPER1 has been associated with both hormone-dependent and independent types of cancer, such as luminal types (which are dependent on ER signaling), epidermal growth factor receptor 2 (HER2), and triple-negative types." (PMID 36231664, 2022).
breast carcinoma (continued). "Molecular mechanistic understanding has revealed that IGFBP1 is a key component of G protein-coupled estrogen receptor 1 (encoded by GPER1) which regulated the sensitivity of breast cancer cells to tamoxifen, and the resistance induced by RG7388 (MDM2 inhibitor) in glioblastoma." (PMID 34737677, 2021). "Also, studies carried out in cancer-associated fibroblasts derived from breast cancer patients show that the GPER-1/EGFR signaling axis increases the expression of several cell cycle regulatory genes." (PMID 33762910, 2021). "In addition, the GPER-1/EGFR signaling axis mediates the expression of cell cycle regulatory genes in cancer-associated fibroblasts derived from breast cancer patients, favoring tumor progression." (PMID 33117280, 2020). "The data described in this contribution provides a link between the G protein-coupled estrogen receptor 1 (GPER1)-mediated IGFBP-1 accumulation associated with tamoxifen treatment in breast cancer cells with the alteration in growth factor signaling previously reported." (PMID 32435229, 2020). "Moreover, we have recently found that GPER-1 down-regulation in breast cancer tissue is associated with poor clinical outcome." (PMID 23849542, 2013). "The dynamic interaction between GPER-1 and signals from the hypothalamus-pituitary- gonads axis suggests a direct connection between sex hormone regulation and molecular events associated with the progression of several types of cancer, especially breast cancer." (PMID 39936103, 2025). "GPER1 plays an important biological role in regulating oestrogenic responses in breast malignancies and has been associated with increased tumour size, increased risk of recurrence and metastasis, decreased survival and therapy resistance in breast cancer patients." (PMID 37921845, 2023). "In IDHwt and IDHmut female tumors, female-specific genes negatively corelated with GPER1 were mainly regulated by miR548, which has been associated with impaired proliferation in various cancers, including glioma and hormone-sensitive tumors such as prostate cancer and breast cancer." (PMID 36077653, 2022). "An association between GPER-1 and insulin-like growth factor (IGF1R) signaling, promoting breast cancer metastasis, has also been suggested." (PMID 39936103, 2025). "In summary, recent research indicates that the involvement of GPER-1 in the regulation of the HPG axis is extremely relevant in the context of breast cancer, as alterations in hormonal signaling promote tumor growth and cancer progression." (PMID 39936103, 2025). "A study using xenografts derived from patients with ER-/PR+ breast cancer (CSCM) has shown that GPER-1 is significantly expressed in these cells." (PMID 39936103, 2025). "Further research is required to increase our understanding of the interactions between GPER-1 and other receptors, and the role those interactions play in breast cancer development." (PMID 39936103, 2025). "GPER-1 in the communication of the hypothalamic-pituitary-gonadal axis, new implications in breast cancer." (PMID 39936103, 2025). "Taken together, these data suggest that GPER-1 modulates a complex signaling network of importance for the development of estradiol-sensitive breast cancer and TNBC, which is influenced by several interrelated factors." (PMID 39936103, 2025). "G Protein-Coupled Estrogen Receptor 1 (GPER-1) is a membrane estrogen receptor that has emerged as a key player in breast cancer development and progression." (PMID 39936103, 2025). "In matched samples of breast cancer and adjacent normal tissues, it has been observed that the tumor suppressor genes GPER1 and miR-339 exhibit reduced expression in Luminal A/B and TNBC subtypes." (PMID 38807590, 2024). "In this situation, miR‐1246 promoted the expression of miR‐1246 precursors and MMP1, which is similar to the upregulation of GPER1 activated by miR‐339 in breast cancer." (PMID 38585233, 2024).
breast carcinoma (continued). "Similar to its effect in breast cancer, GPER1 promotes cell proliferation, migration, lymph node metastasis and invasion in ER-negative ovarian cancer, and its overexpression correlates with tumor size and stage." (PMID 39252786, 2024). "For example, miR-339 upregulates the expression of G protein-coupled estrogen receptor 1 (GPER1) in breast cancer cells by switching on the GPER1 enhancer to repress cell proliferation." (PMID 38750489, 2024). "Ful has previously been shown to activate the G protein-coupled estrogen receptor 1 (GPER1) in breast cancer cells." (PMID 39619437, 2024). "Further mechanistic studies have uncovered that miR-339 enhances GPER1 expression in breast cancer cells by activating the GPER1 enhancer." (PMID 38807590, 2024). "Weißenborn’s findings demonstrated that the GPER1-specific agonist G-1 activates GPER1 in a concentration-dependent manner, effectively inhibiting breast cancer cell growth." (PMID 37921845, 2023). "In parallel, there is an ever-increasing interest in GPER1 as a target in the context of several cancers, particularly breast cancer." (PMID 37947649, 2023). "Recent meta-analysis results correlate elevated GPER1 mRNA expression with improved survival rates in breast cancer patients." (PMID 37921845, 2023). "The ERα isoform ER-α36 was demonstrated to mediate nongenomic responses to estrogen through high-affinity binding to E2 and even the GPER1-specific agonist G-1 in SKBR-3 breast cancer cells and transfected HEK293T cells." (PMID 37947649, 2023). "Several studies found that environmental estrogens promoted the growth and development breast of breast cancer xenograft tumor in nude mice by activating ERα or GPER1." (PMID 36497816, 2022). "In conclusion, ERα and GPER1 show promising roles in breast cancer development, whereas the role of ERβ remains controversial." (PMID 36060947, 2022). "Approximately 75% of breast tumors showed the positive expression of ERα and approximately 50% of breast cancer showed positive expression of GPER1." (PMID 36497816, 2022). "The study provided a novel perspective to evaluate the adverse health impacts of BPAF on breast cancer patients with GPER1-positive expression." (PMID 36497816, 2022). "The pharmacological effect of BPA in breast cancer cells is mediated through G protein-coupled estrogen receptor 1 (GPER)." (PMID 36385271, 2022). "GPER1 is expressed in normal mammary epithelium and up to 60% of breast cancer tissues, either in ER-positive or TNBC." (PMID 36555323, 2022). "Contrary to its promoting function in breast cancer and endometriosis, GPER1 activation inhibits the growth of normal and malignant bladder urothelial cells." (PMID 36060947, 2022). "The SK-BR-3 cells are human breast cancer cells with GPER1-positive expression, which are very sensitive to estrogen chemicals." (PMID 36497816, 2022). "Different articles have shown that GPER1 can confer resistance to conventional estrogen-dependent breast cancer treatment." (PMID 36231664, 2022). "Along these lines, the direct contact of breast cancer cells with CAFs transferred G protein-coupled estrogen receptor 1 (GPER) to the cytoplasm." (PMID 34769066, 2021). "In contrast to ESRs, GPER1 is widely expressed in breast cancers including TNBCs, which mediates the rapid signal response of estrogen and is related to the drug resistance of tamoxifen and other drugs." (PMID 34768896, 2021). "In Rigiracciolo's work, GPER1 was involved in the cross-talk with MR in the aldosterone-induced proliferation of breast cancer cells." (PMID 34239558, 2021). "For instance, the oncogenic estrogenic G-protein-coupled estrogen receptor 1 (GPER) signaling pathway is known to decrease miR-148 levels in breast cancer cells, contributing to cancer immune evasion." (PMID 34122412, 2021). "This response is a result of GPER-1 overexpression attributed to the prolonged treatment of breast cancer cells with the drug." (PMID 33117280, 2020).